CRTC2 (CREB regulated transcription coactivator 2)
Diseases named in the same sentence as CRTC2 in open-access papers (continued):
Sharing a sentence is not in itself a finding about the gene and the disease.
tumor (24 papers, 2008 to 2026). "Of note, CRTC2-CA or CREB-CA normalized TRPM7 deficiency-induced defects in tumor growth, glucose consumption, as well as SLC2A3 expression." (PMID 36878949, 2023). "Our data have validated that TRPM7 deficiency reduces tumor and EC glycolytic metabolism by inactivating the CRTC2/CREB axis." (PMID 36878949, 2023). "CRTC2 is not only highly expressed in a variety of tumors, but also has been proven by a large number of studies that CRTC2 is also closely related to chemotherapy resistance of tumor cells." (PMID 37151390, 2023). "Mechanically, hypomethylation‐induced CRTC2 high expression promoted the malignant development of HCC by activating the Wnt pathway and affecting the anti‐tumour immune response." (PMID 39462685, 2024). "Several of these EPINs have promoters of differentially expressed genes (such as DLL1, STOM and SEC11C in the GEPIA tumor/normal dataset; ID2, RPS27, SEC11C, CASZ1, CRTC2, C5 and STOM in the LNCaP/LHSAR dataset; see Methods, Differential Gene Expression)." (PMID 38057321, 2023). "SIRT1 is a NAD+-dependent Class III histone deacetylase that has been shown to antagonize cellular senescence and is also an established negative regulator of CRTC2, and possibly CRTC1 as well, suggesting that this integration event could enhance CRTC1-MAML2 expression in this tumor." (PMID 36366450, 2022).
infection (6 papers, 2014 to 2025). The state of being infected such as from the introduction of a foreign agent such as serum, vaccine, antigenic substance or organism. "Infection of VSMC with Ad:CRTC2S171A or Ad:CRTC3S161A resulted in equal expression of FLAG-tagged CRTC2 and CRTC3 protein and a significant increase in CREB activity." (PMID 29559698, 2018). "Elucidating the regulatory role of the CRTC2/PGC1α signaling pathway and the underlying mechanism will reveal important molecular processes involved in HBV biosynthesis and elucidate the relationship between metabolic signals and HBV replication during natural infection." (PMID 24529027, 2014). "Furthermore, only one of these genes, CREB-regulated transcription coactivator 2 (CRTC2), which was downregulated following BpΔbteA infection, showed restored expression upon infection with a complemented strain BpΔbteA::bteA." (PMID 40757824, 2025).
metabolic disease (2 papers, 2022 to 2025). A congenital disorder (due to inherited enzyme abnormality) or acquired (due to failure of a metabolically important organ) disorder resulting from an abnormal metabolic process. "The elucidation of the glycogen/AMPK/CRTC2 signaling pathway may potentially provide new therapeutic approaches for metabolic diseases." (PMID 40454488, 2025).
CRTC2 also shares sentences with these, for which no sentence is quoted: bladder cancer (3 papers); hyperlipidemia (3); breast carcinoma (2); glial tumors (2); Hyperinsulinemia (2); iron deficiency (2); prostate carcinoma (2); acute lymphoblastic leukemia (1); acute myeloid leukemia (1); adenocarcinoma (1); adenovirus infection (1); cardiac disease (1); cardiomyopathy (1); cardiovascular diseases (1); chronic myeloid leukemia (1); cystic renal disease (1); glioblastoma (1); Glioma (1); Glucose intolerance (1); hepatic cancer (1); Hypertension (1); Infertility (1); kidney failure (1); latent infections (1); lymphoid neoplasm (1); lymphoma (1); melasma (1); memory impairment (1); multiple myeloma (1); non-alcoholic fatty liver disease (1).
A further 8 diseases each share a sentence with CRTC2 in 1 paper.